BRCA2 (BRCA2 DNA repair associated)
Diseases named in the same sentence as BRCA2 in open-access papers (continued):
Sharing a sentence is not in itself a finding about the gene and the disease.
breast cancer (continued). "In the present study, we identified two mutations, namely, Q563X (BRCA1) and N3124I (BRCA2), showing a strong founder effect in the Polish patients with a hereditary risk of ovarian/breast cancer." (PMID 25948282, 2015). "In humans, recent study showed that single nucleotide polymorphisms around the BRCA2 gene affected the expression levels of human BRCA2 mRNA and increased breast cancer risk." (PMID 26202431, 2015). "Best-evidence synthesis: a summary of the available evidence for the relation between BRCA2 mutation carriership and breast cancer prognosis." (PMID 25816289, 2015). "Of interest, germline mutations in BRCA1 versus BRCA2 associate with different subtypes of breast cancer." (PMID 25869442, 2015). "A woman’s risk for breast cancer increases to 45% to 65% by age 70 if she carries a mutation in either the BRCA1 or BRCA2 gene (Centers for Disease Control and Prevention [CDC], 2014; Chen & Parmigiani, 2007; NCI, 2015)." (PMID 26557407, 2015). "BRCA1 and BRCA2 mutation carriers <70 years old face a 57% and 49% (respectively) risk of developing breast cancer." (PMID 26010605, 2015). "Strikingly, the sensitivity of mammography in diagnosing breast cancer is lower in BRCA1 mutation carriers compared to BRCA2 mutation carriers or women with a moderate to high familial breast cancer risk." (PMID 26000714, 2015). "The study of gene loci functionally related to HMMR suggests an association between variation in AURKA/CSTF1 and risk of breast cancer among BRCA2 mutation carriers." (PMID 25830658, 2015). "Many cases of hereditary breast cancer are due to mutations in either the BRCA1 gene or the BRCA2 gene." (PMID 25910040, 2015). "The rare germline pathogenic BRCA1 mutations increase the risk of breast and ovarian cancer to approximately 80% and 60%, respectively, whereas BRCA2 mutations increase breast cancer risk to more than 80% by the age of 80." (PMID 25948282, 2015). "Only 10% to 24% of BRCA1-associated breast cancers are estrogen receptor–positive, whereas 65% to 79% of BRCA2-associated breast cancers are positive for this receptor." (PMID 26557407, 2015). "Germline mutations in BRCA1 or BRCA2 lead to a high lifetime probability of developing ovarian or breast cancer." (PMID 25859162, 2015). "Increased risk of breast cancer associated with rs3803662 was confirmed in BRCA1/BRCA2 mutation carriers." (PMID 26239137, 2015). "Recently it was suggested that the risk to develop breast cancer for PALB2 mutation carriers is as high as the risk borne by BRCA2 mutation carriers." (PMID 26577449, 2015). "It is estimated that approximately 10% of men with breast cancer have a genetic predisposition, with BRCA2 being the most prevalent gene mutation and BRCA1 being less." (PMID 25632310, 2015). "Other genomic variations (for example, in genes encoding proteins interacting with BRCA1 and BRCA2) have been identified as modifiers of breast cancer risk and increase or decrease the risk initially conferred by BRCA1 or BRCA2 mutation." (PMID 25925750, 2015). "Genetics report 1 (a female breast cancer patient with a strong family history) provided the reader with the following summary “missense mutation in exon 11 of the BRCA2 gene”." (PMID 26608569, 2015). "These mostly entailed up-regulated miRNAs in sporadic breast carcinomas and down-regulated in BRCA2-associated breast carcinomas (miR-20a-5p, let-7f-5p, and miR-29b-3p)." (PMID 26378051, 2015). "miRNA profiles of 17 BRCA1- and 9 BRCA2-associated breast carcinomas were analyzed using microarrays." (PMID 26378051, 2015). "qRT-PCR analysis of miR-99a confirmed the microarray results showing that it was down-regulated in both BRCA1- and BRCA2-associated breast carcinomas compared to their normal breast tissue counterparts." (PMID 26378051, 2015).
breast cancer (continued). "This would be very interesting as BRCA2-associated and sporadic breast carcinomas show many similarities in histology and protein expression." (PMID 26378051, 2015). "We and others have shown specific somatic profiles of CNAs characteristic for both BRCA1 and BRCA2-associated breast carcinomas." (PMID 26553136, 2015). "The GPS score had a protective effect in the whole BRCA1 population and in the ovulating strata (RH 0.76/0.58, p > 0.015), and was associated to a higher hazard of breast cancer in the BRCA2 whole population (RH = 1.33, p = 0.035)." (PMID 25274085, 2014). "Hereditary BRCA1 and BRCA2 mutations account for about 60% of inherited breast cancer and are the only known causes of hereditary breast cancer syndrome." (PMID 24711893, 2014). "Family history profiles can predict BRCA1 or BRCA2 mutation, mainly those characterized by first-degree relatives with ovarian cancer or breast cancer along with young age at diagnosis, bilateral occurrence and increased number of affected relatives." (PMID 24591761, 2014). "Routine screening detected the Portuguese founder mutation BRCA2 c.156_157insAluYa5 in a Galician woman in whom breast cancer was diagnosed at 41 years of age." (PMID 24686251, 2014). "Olgaet et al27 reported that an intronic mutation (c.6937 + 594T > G) can activate a cryptic exon in BRCA2 that disrupts the coding sequence in breast cancer families." (PMID 25034901, 2014). "Women with a strong family history of cancer who possess a harmful BRCA1 or BRCA2 allele are at high risk for developing breast cancer within their lifetime (80% and 60%, respectively)." (PMID 25011685, 2014). "The prevalence rate of BRCA1 and BRCA2 mutations in this study is the lowest reported in South American studies with breast cancer populations unselected for age or family history." (PMID 24742220, 2014). "A strong family history of breast cancer and/or carrying a germline mutation in the BRCA1 or BRCA2 gene, substantially increases breast cancer risk." (PMID 26034659, 2014). "Over the past decade, many studies were conducted to evaluate the association between BRCA2 N372H polymorphism and the risk of cancer, mainly breast cancer." (PMID 25348552, 2014). "In another study, 29 BRCA2 variants were detected in Cypriot families with family history of breast cancer." (PMID 24678344, 2014). "Results of our investigation and data had been previously published from Iran indicate that the common BRCA2 mutations are infrequent in Iranian breast cancer patients." (PMID 24711893, 2014). "Women with BRCA1 mutations typically develop breast cancer at an earlier age than BRCA2-related and sporadic breast cancers." (PMID 24579064, 2014). "FANCD2 (12th) interacts with the BRCA1 and BRCA2 genes in the DNA repair process to reduce the risk of breast cancer." (PMID 24564336, 2014). "Whilst BRCA1 and BRCA2 are considered “high risk” the other five members of this network component are considered “moderate risk” with a two- to fourfold increased breast cancer risk relative to the general population (10%)." (PMID 24550935, 2014). "Yearly imaging with MRI has been shown to be a more sensitive means of screening for breast cancer than annual mammography for women at a high risk of cancer due to a BRCA1 or BRCA2 mutation, or at moderate risk of cancer due to a strong family history." (PMID 24667084, 2014). "The current study provides evidence that genomic patterns resembling BRCA1- or BRCA2-mutated breast cancers can identify breast cancer patients with TN as well as ER-positive, HER2-negative tumors that are sensitive to intensified, DSB-inducing chemotherapy." (PMID 24887359, 2014). "In BRCA1- or BRCA2-mutated breast cancer, significant but transient and inconstant objective responses have been observed to olaparib in some studies, while other results were less conclusive." (PMID 25144364, 2014).
breast cancer (continued). "The prevalence of BRCA1 LGRs ranges from approximately 6%–27% of all mutations detected in the BRCA1 gene; BRCA2 LGRs play a minimal role in breast cancer." (PMID 25176351, 2014). "Approximately 20-25% of familial breast cancers can be attributed to a germline mutation in BRCA1 or BRCA2." (PMID 24667084, 2014). "The strongest evidence of association was observed for rs1466785 in the NEIL2 gene (HR: 1.09, 95% CI (1.03–1.16), p = 2.7×10−3) for association with breast cancer risk in BRCA2 mutation carriers." (PMID 24698998, 2014). "It has been know that mutation in BRCA2 is related to not only increased breast cancer risk, but also increased risk of the ovary, prostate, pancreas, and male breast, partially due to impaired capacity of repairing DNA DSBs." (PMID 25348552, 2014). "Such mutations and sequence variants of BRCA1 and BRCA2 genes were previously identified in a group of Sri Lankan breast cancer patients." (PMID 24906410, 2014). "Two meta-analyses have been carried out to attempt to evaluate the association between BRCA2 N372H and risk of breast cancer." (PMID 25348552, 2014). "A founder mutation in BRCA2 was identified in a different study of Cypriot families with history of breast cancer." (PMID 24678344, 2014). "Patients with tumors with similar aCGH patterns as BRCA1- and/or BRCA2-mutated breast cancers were defined as having a BRCA-likeCGH status, others as non-BCRA-likeCGH." (PMID 24887359, 2014). "BRCA1 and BRCA2 are the two major susceptibility genes involved in hereditary predisposition to breast cancer." (PMID 24834114, 2014). "Three previous studies have evaluated the prevalence of BRCA1 and BRCA2 mutations in breast cancer cases in the Colombian population." (PMID 24742220, 2014). "The high-risk and well characterized tumor suppressor genes BRCA1 and BRCA2 are thought to be responsible for the majority of hereditary breast cancer, with germline mutations conferring a life-time risk of 55–85% and 35–60% respectively." (PMID 24830819, 2014). "These analyses demonstrated that, despite the lack of an association between some susceptibility variants and overall breast cancer risk for BRCA1 or BRCA2 carriers, residual associations exist with specific disease subtypes." (PMID 25919761, 2014). "Although BRCA1 and BRCA2 account for a high percentage of hereditary cases, there are more than 25 susceptibility genes that differentially impact the risk for breast cancer." (PMID 24830819, 2014). "Women with harmful mutations in either BRCA1 or BRCA2 have a risk of breast cancer that is about five times the normal risk, and a risk of ovarian cancer which is about ten to thirty times the normal risk." (PMID 24523856, 2014). "No frame shift or missense mutations were detected in any of the exons 2 and 11 of BRCA2 gene in early onset breast cancer patients in Iranian Azeri-Turkish women." (PMID 24711893, 2014). "The screening of BRCA1 and BRCA2 mutations is now an established component of risk evaluation and management of familial breast cancer, early-onset breast cancer and bilateral breast cancer patients." (PMID 24961674, 2014). "Approximately half of all hereditary breast cancers are due to a mutation in either BRCA1 or BRCA2, and approximately 80% of individuals with a mutation in either of these genes develop breast cancer by the age of 70 years." (PMID 24950059, 2014). "The BRCA1 and BRCA2 mutations together account for about 20–25% of hereditary breast cancers and about 5–10% of all breast cancers." (PMID 25374621, 2014). "Germline mutations in BRCA1 and BRCA2 only explain the breast cancer risk in approximately one fourth of these families, however, it is expected that additional BRCA1/2 mutations still remain undetected by the screening methods used today." (PMID 24479546, 2014).
breast cancer (continued). "This is a known disease causal mutation (c.5946delT in BRCA2) in the sample with hereditary breast cancer, and this mutation was verified by visualizing alignment on Integrative Genomics Viewer19." (PMID 25034901, 2014). "For example, mutations in BRCA1 (breast cancer 1, early onset) and BRCA2 (breast cancer 2, early onset) are important risk factors for PC." (PMID 25183411, 2014). "Estimated lifetime breast cancer risk for male BRCA2 carriers is approximately 8%, while there is high relative risk for pancreatic and prostate cancer, when compared to the general population." (PMID 24660075, 2014). "Stratification by BRCA1/BRCA2 mutation status showed that the occurrence of contralateral breast cancer was eight fold higher among mutation carriers compared with non-carriers." (PMID 24834114, 2014). "Numerous studies have investigated association between BRCA2 N372H polymorphism and risk of several cancers, especially breast cancer." (PMID 25348552, 2014). "Women who carry pathogenic mutations in BRCA1 or BRCA2 have markedly increased risks of developing breast cancer." (PMID 25919761, 2014). "We performed mutation analysis of BRCA1 and BRCA2 on unselected patients with breast cancer from the region of Medellin, Colombia." (PMID 24742220, 2014). "Given the reported low frequency of mutations in BRCA1 and BRCA2 in Sudanese breast cancer patients, the methylation status of six tumor suppressor genes was investigated using methylation specific PCR." (PMID 24607238, 2014). "Mutations in BRCA1 and BRCA2 genes are associated with predisposition to breast cancer; hence we have screened both the cell lines for mutations/ polymorphisms in these genes." (PMID 24502646, 2014). "Point mutations and sequence variants in BRCA1 and BRCA2 genes were previously identified in this cohort of Sri Lankan breast cancer patients." (PMID 24906410, 2014). "The aim of this study was to assess the contribution of BRCA1and BRCA2 rearrangements for predisposing to breast cancer in familial breast cancer patients and at risk individuals in Sri Lanka." (PMID 24906410, 2014). "The same SNP has previously been reported as associated with increased breast cancer risk for BRCA2 mutation carriers." (PMID 24852296, 2014). "The risk of developing breast or ovarian cancer in individuals with certain cancer-associated BRCA1/BRCA2 alleles is 60-80% for breast cancer and 20-40% for ovarian cancer." (PMID 25051360, 2014). "In summary, our investigations have provided information of clinical utility for 18 of 19 BRCA1 or BRCA2 variants identified by clinical germline testing of breast cancer patients." (PMID 24489791, 2014). "Studies have found that BRCA1 mutations lead to a breast cancer risk of 40 to 87% and an ovarian cancer risk of about 16 to 68% by age 70, while BRCA2 mutations lead to a breast cancer risk of 40 to 84% and an ovarian cancer risk of 11 to 27% by that age." (PMID 23885284, 2013). "Median age of diagnosis was 42 years among BRCA1, 43.5 years among BRCA2 mutation carriers, and 61 years for sporadic breast cancer patients." (PMID 23704984, 2013). "In further stratified analysis, significantly elevated breast cancer risk was observed in BRCA2 mutation carriers (recessive model: OR = 4.88, 95% CI = 1.10–21.67; additive model: OR = 4.92, 95% CI = 1.11–21.83)." (PMID 24040396, 2013). "In the largest assemblage of BRCA2 mutation carriers, we identified a novel locus at 6q24 that is associated with breast cancer risk, and noted two potential SNPs of interest at Xq26 and 2p22." (PMID 23544012, 2013). "Approximately 1 in 800 people carries a BRCA1 (breast cancer 1, early onset) mutation and approximately 1 in 500 people carries a BRCA2 (breast cancer 2, early onset) mutation." (PMID 23885284, 2013). "BRCA1 and BRCA2 are classically defined as breast cancer susceptibility genes but each is also somatically altered in a number of tumor types including ovarian, prostate and colon." (PMID 24202319, 2013).
breast cancer (continued). "Even though some women are genetically predisposed by inheriting the BRCA1 and BRCA2 genes, studies show that an elevated lifetime of estrogen exposure is also another risk factor for breast cancer." (PMID 23762568, 2013). "Mutations in some of these, like BRCA1 and BRCA2, are extremely rare, but confer high risks to breast cancer, others are common but only confer a minor increase in risk." (PMID 23383274, 2013). "A high-throughput pharmaceutical screen on BRCA2-deficient mouse mammary tumor cells pointed at potential efficacy of a well-known alkylating cytotoxic drug, melphalan." (PMID 23548133, 2013). "Meta-analysis of RAD51 135G>C polymorphism and breast cancer association according to BRCA1/BRCA2 mutation." (PMID 24040396, 2013). "Since the discovery of the breast cancer susceptibility genes BRCA1 and BRCA2 in 1994, a total of 18 breast cancer-associated susceptibility genes have been identified." (PMID 23318652, 2013). "To comprehensively identify breast cancer risk modifying loci for BRCA2 mutation carriers, we conducted a deep replication of an ongoing GWAS discovery study." (PMID 23544012, 2013). "In recent years there has been increased penetrance of BRCA1 and BRCA2 associated breast cancer, prompting investigation into the role of modifiable risk factors in this group." (PMID 23517070, 2013). "BRCA1 and BRCA2 are the most important genetic factors in hereditary breast cancer in the Han Chinese population, but the mutation rates are lower than in other ethnic groups." (PMID 23318652, 2013). "Demonstrating proof-of-principle, studies of olaparib, a potent oral PARP inhibitor, have demonstrated monotherapy activity and acceptable toxicity in patients with ovarian or breast cancer who have a germline BRCA1 or BRCA2 mutation." (PMID 24063698, 2013). "Mutations in PALB2 predispose to breast cancer and gastric cancer, and the penetrance for breast cancer in Finnish multiple-case families has been found similarly high as for BRCA2 mutations." (PMID 24025454, 2013). "Recent studies have revealed that BRCA1 and BRCA2 germline mutation-related breast cancers show frequent overexpression of hypoxia inducible factor-1α (HIF-1α), the key regulator of the hypoxia response." (PMID 23409121, 2013). "Variants such as p.R1699Q in BRCA1 or p.K3326X in BRCA2 seem to be associated with rather low, though significant, breast cancer risks." (PMID 24025454, 2013). "We also replicated associations with known breast cancer susceptibility SNPs previously reported in the general population and in BRCA2 mutation carriers." (PMID 23544012, 2013). "Carriers of BRCA1 or BRCA2 (BRCA1/2) mutations are at particularly high risk of breast cancer, with a 45-65% cumulative risk by age 70 years." (PMID 23837641, 2013). "Ataxia telangiectasia presents with a significant increased all-cause cancer risk consistent with its critical repair role and inherited HR protein BRCA1 and BRCA2 mutants strongly predispose toward breast cancer, prostate, and colon cancer." (PMID 24364026, 2013). "High-penetrance breast cancer susceptibility genes, such as BRCA1 and BRCA2, explain only a small fraction of breast cancers in the general population because of their low mutation rates." (PMID 23976942, 2013). "Examples include ASE of the APC and TGFBR1 gene which has been associated with colorectal cancer or ASE of BRCA1 and BRCA2 in breast cancer." (PMID 23383130, 2013). "Genetic BRCA2 insufficiency is associated with breast cancer development; however, in sporadic breast cancer cases, high BRCA2 expression is paradoxically correlated with poor prognosis." (PMID 24289229, 2013). "Most breast cancer cases with germline BRCA2 mutations have loss of heterozygosity at the BRCA2 locus, resulting in the loss of the BRCA2 allele." (PMID 24289229, 2013). "Testing for mutations in the BRCA1 and BRCA2 genes among high-risk breast cancer patients has become a routine practice among clinical geneticists." (PMID 23941127, 2013).